TLR2 (toll like receptor 2)
Diseases named in the same sentence as TLR2 in open-access papers (continued):
Sharing a sentence is not in itself a finding about the gene and the disease.
Sepsis (continued). "The aim of our study was to investigate the possible associations between expression of TLR2, TLR4 and TLR9 and occurrence of sepsis in patients treated with intensive induction chemotherapy for AML." (PMID 25412934, 2014). "TLR2 has been shown to be overexpressed in septic shock and also to play a role in acute kidney injury, which is an important consequence of severe sepsis and was part of our severity criteria." (PMID 24612859, 2014). "The aim of this study was to investigate the associations between expression of TLR2, TLR4 and TLR9 and occurrence of sepsis in patients treated with intensive induction chemotherapy for AML." (PMID 25412934, 2014). "TLR2 expression (p < 0.05) was higher and HLA-DR lower (p < 0.05) on monocytes of patients with severe sepsis compared to patients with simple sepsis." (PMID 23414215, 2013). "TLR4 and TLR2 are favorite targets for developing anti-sepsis drugs, and antagonistic compounds have shown efficient protection from septic shock in pre-clinical models." (PMID 24302927, 2013). "SNPs in the genes for TLR2 (rs3804099), TLR5 (rs5744105), IL-10 (rs1800896), and PLA2G2A (rs1891320) were associated with sepsis." (PMID 24310803, 2013). "Mainly for historical reasons and because of their ligand specificity, TLR4 and to a lesser extent TLR2 are the favorite targets for developing anti-sepsis drugs." (PMID 24302927, 2013). "A key tissue in sepsis is the endothelium, which expresses TLR2 and TLR4 receptors, known regulators of inflammatory mechanisms and potential therapeutic targets for this pathology." (PMID 23552565, 2013). "Results from clinical trials evaluating anti-TLR4 and anti-TLR2 approaches are presented, discussing the challenges of study design in sepsis and future exploitation of these agents in infectious diseases." (PMID 24302927, 2013). "Our results show that postconditioning with sevoflurane using an experimental in vitro model of sepsis exerts protective effects on cell viability, reducing TLR2 and TLR4 expression as well as inflammatory markers in human endothelial cells." (PMID 23552565, 2013). "TLR2 appears to contribute to mouse survival in a model of Staphylococcus-induced septicemia, but only against intravenous challenge with 107 bacteria." (PMID 23316483, 2012). "Most interestingly, the percentage of NK cells expressing intracellular TLR2 was significantly increased in sepsis for the CD56dim subset." (PMID 23098236, 2012). "The percentage of intracellular TLR2-positive CD56dim NK cells was significantly increased in sepsis and SIRS patients compared to healthy controls." (PMID 23098236, 2012). "The expression of TLR2 molecule on polymorphonuclear granulocytes was studied with respect to infection, sepsis, surgical stress, or other medical intervention." (PMID 23304186, 2012). "TLR2 activation by lipopeptides 24 h after a low-dose staphylococcal infection results in lethal sepsis with increased bacterial load and a very large decrease of neutrophil numbers." (PMID 23316483, 2012). "In kidney tissue after sepsis, TLR2 and TLR4 mRNA is highly expressed in the WT mice, which also have a six-fold increased expression of MyD88." (PMID 22655058, 2012). "Recent studies showed that extracellular histones are major mediators of death in animal models of sepsis and that histones activate TLR-2 and TLR-4." (PMID 22889177, 2012). "Great deal of effort has been invested particularly into the development of TLR4 antagonists for sepsis and antibodies against TLR2 or TLR4 have shown some promising results for the therapy of sepsis." (PMID 23305364, 2012). "In studies focusing on infection or sepsis, associations have been described for SNPs in the TLR1 (rs5743551), TLR2 (rs5743708), TLR4 (rs4986790 and rs4986791), TLR9 (rs5743836), IRAK1 (rs1059703), and TIRAP genes (rs8177374 and rs7932766)." (PMID 21219635, 2011).
Sepsis (continued). "Hepatic VLCAD levels decreased in WT and especially in TLR2−/− mice in sepsis, but increased in TLR4−/− mice relative to the outer membrane reference protein porin." (PMID 21966468, 2011). "Five genes, namely TLR2, TLR4, TLR9, MyD88 and TOLLIP, were investigated for their association with sepsis susceptibility by a tag single nucleotide polymorphism (SNP) strategy." (PMID 21219635, 2011). "On par with this concept, TLR2 or MyD88 KO mice have been demonstrated to be resistant to sepsis, indicating that TLR2 mediated signaling is playing an important role in the survival of bacterial pathogens." (PMID 21124939, 2010). "Highly pathogenic S. suis could persistently induce cytokines mainly by TLR2 pathway, and eventually the high level of cytokines and toxins secreted by phagocytosis-resistant bacteria could destroy deep tissues, and cause meningitis, septicaemia, pneumonia, endocarditis, and arthritis." (PMID 20937098, 2010). "Cell activation via TLR2 and other pattern recognition receptors (PRRs) contributes to sepsis pathology and chronic inflammation both relying on overamplification of an immune response." (PMID 20388199, 2010). "The relationship between gene polymorphisms in TLR1, TLR2, TLR4 and sepsis, and MODS has been well studied." (PMID 21274447, 2010). "The finding that TLR2(−/−) mice have preserved contractile performance compared to WT mice in the setting of S. aureus induced sepsis, serves as a proof for the link between cardiac TLR2 activation and depressed cardiac function." (PMID 20628516, 2010). "In human sepsis increased protein expression and mRNA of TLR2 and TLR4 on blood neutrophils and monocytes are found compared to healthy individuals." (PMID 19371402, 2009). "In patients with sepsis, death was associated with significant lower CD14 and TLR2 expression at admission (CD14: 25.7 +- 19.1 vs 39.1 +- 17.3 mean fluorescence intensity [MFI], p = 0.02; TLR2: 21.8 +- 9.4 vs. 30.9 +- 9.6, p = 0.01)." (PMID 19371402, 2009). "The comparison among the four groups showed a trend to significance (p = 0.08) with lower TLR2 expression in the septic shock group compared to the control group (p = 0.05), to the sepsis group (p = 0.03) and severe sepsis group (p = 0.04)." (PMID 18302745, 2008). "Additionally, BCG-derived outer membrane vesicles can induce TLR2-dependent trained immunity to prevent polymicrobial sepsis, providing new ideas for the prevention and treatment of sepsis." (PMID 41195185, 2025). "TLR2 is present on cell plasma membranes and intracellular endosomes to respond to bacteria that have been internalised and is involved in the production of cytokines in response to sepsis." (PMID 39968295, 2025). "Given the significant blocking effects of HS14 and dHG-5 on platelet TLR2, these compounds may possess considerable potential for therapeutic applications in conditions such as sepsis, atherosclerosis, and rheumatoid arthritis." (PMID 40137296, 2025). "Furthermore, the blockade of TLR2 or TLR4 signaling by antagonistic antibodies or small molecule inhibitors successfully decreases disease severity in sepsis mouse models 13-15." (PMID 40963927, 2025). "TLR2 and TLR4 are the primary TLRs implicated in sepsis-related cardiac injury." (PMID 40386784, 2025). "Given that bacteria can directly induce platelet activation via TLR2, inhibiting this pathway may be a potential strategy to mitigate or delay the progression of sepsis." (PMID 40137296, 2025). "It has been found that TLR4 knockout mice are resistant to Gram-negative bacteria-induced septic shock 11, and TLR2-deficient mice have increased survival rates compared to wild-type mice in a polymicrobial sepsis model." (PMID 40963927, 2025). "Whereas TLR2 and 4 can affect myocardial contractile function in sepsis." (PMID 40356926, 2025).
Sepsis (continued). "Additionally, TsAg conferred a therapeutic effect on sepsis-induced acute lung injury through activating Tregs and inhibiting pro-inflammatory cytokinesvia the high mobility group box 1/TLR2/MYD88 signaling pathway." (PMID 39314046, 2024). "Animal experiments further support the involvement of TLRs in sepsis and pneumococcal lung infection: mice with experimental sepsis exhibit a cytokine pattern dependent on NF-κB and MAPKs and TLR2 and TLR4 knockout (KO) mice display less effective cytokine release compared with wild mice." (PMID 38835761, 2024). "This study shown that silenced-C5ar1 inhibited the degree of NET and TLR2 suggesting silenced-C5ar1 may improve the sepsis via the Toll-like receptor signaling pathway." (PMID 38165570, 2024). "In murine models of sepsis, TLR2 and TLR4 are upregulated in hepatic and splenic macrophages." (PMID 38835761, 2024). "When sepsis occurs, pro-inflammatory factors and high mobility group box-1 protein (HMGB1) passively released from dead cells cause the up-regulation of programmed death-ligand 1 (PD-L1) through Toll-like Receptor 2 (TLR2) on neutrophils." (PMID 39877653, 2024). "We tested the hypothesis that aging exacerbates cardiac dysfunction in sepsis through a Toll-like receptor 2 (TLR2)-dependent mechanism." (PMID 38094127, 2023). "The expression of TLR-2/MyD88 in tissues was measured by western blot to determine whether TLR-2/MyD88 is involved in the sepsis-induced inflammatory signaling pathway." (PMID 38066526, 2023). "In addition, some studies have confirmed that NEAT1 alleviates sepsis-induced myocardial injury by regulating TLR2/NF-κB signaling pathway." (PMID 36817458, 2023). "Thus, elevated TLR2 level/activity mediates inflamm-aging, resulting in exaggerated inflammation and cardiac dysfunction during sepsis in old mice." (PMID 38094127, 2023). "Thus, elevated levels of TLR2 in multiple organs, including the heart, drive sepsis severity in old mice." (PMID 38094127, 2023). "In the study, mimics miR-22 could remarkably downregulate the LPS-induced increased TLR4, TLR2, MyD88, and p-NF-κB p65 protein expression, which indicated that miR-22 may alleviate sepsis-induced AKI by targeting HMGB1/TLR4/NF-κB signaling pathway." (PMID 35960478, 2023). "Beyond M. pneumoniae pneumonia, the total flavonoids from C. oleifera defatted seeds might benefit in the treatment of other conditions, particularly those related to TLR2 activation, like sepsis and Clostridium difficile infection." (PMID 37894556, 2023). "Previous study found that anti-TLR2 treatment improved survival in young mice with severe sepsis." (PMID 38094127, 2023). "Based on these findings, we tested the hypothesis that elevated TLR2 levels augment inflammatory activity in sepsis and thereby results in worse cardiac dysfunction." (PMID 38094127, 2023). "Therefore, the TLR2/MyD88 signaling pathway can serve as an essential marker for the severity of sepsis and treatment efficacy." (PMID 38066526, 2023). "The results indicated that the anti-inflammatory effect of EgCF on serious bacterial infections such as sepsis may take place through inhibition of the TLR2 and MyD88 inflammatory signaling pathway." (PMID 38066526, 2023). "Thus, TLR2 mediates the inflammatory response to sepsis and occupies a major role in elevating the inflammatory activity in old septic mice." (PMID 38094127, 2023). "It is not understood why viral infections can also cause sepsis although viruses do not express ligands for TLR-4 or TLR-2, the prototypic TLRs involved in bacterial sepsis and septic shock." (PMID 36851312, 2023). "As exemplified by a TLR-2 and NF-κB dependent luciferase assay (p = 0.0004) and greater baseline cytokine concentrations, inflammatory activity was increased in plain samples from sepsis patients compared to controls." (PMID 35981050, 2022). "Only wt-EVs were capable to mount sepsis-like reactions and TLR2 and TLR4 activation." (PMID 35203650, 2022).
Sepsis (continued). "Identification of the role of TLR2 and TLR4 polymorphisms in developing infection and sepsis could allow early prediction, prevention, and management of these serious diseases." (PMID 36142893, 2022). "CLP induced the expansion of the TN, TCM, and TVM subpopulations and an increased expression of CD69 on TN and TVM cells in the BM of TLR2−/− mice in a similar pattern as observed for WT mice, which argues against a role of TLR2 in the activation of CD8 T cells during sepsis." (PMID 36148245, 2022). "Thus, agonists of TLR2 are responsible for the reduced IFN-γ synthesis of CD8+ T cells in the BM during sepsis." (PMID 36148245, 2022). "Therefore, purified CD8+ T cells from WT or TLR2−/− mice were adoptively transferred into congenic CD45.1+ WT mice before induction of sepsis." (PMID 36148245, 2022). "Recent evidence also suggests that TLR2 may be one of the major contributors to the pathogenesis of sepsis." (PMID 35986268, 2022). "The remarkable importance of TLR2 and TLR4 in our immune system and in modulating our response to infection suggested potential roles of their important variants, Arg753Gln and Asp299Gly, in increasing susceptibility to infection and sepsis as well." (PMID 36142893, 2022). "Despite a lack of larger studies demonstrating an association between TLR4 and biomarkers like PCT and CRP in diagnosis of sepsis, results of a recent study conclude the possibility of using TLR2 and TLR4 expression to determine the severity of sepsis as a diagnostic biomarker (p < 0.05)." (PMID 33803628, 2021). "The activation of innate immune receptors by fungi generally follows the same pattern as bacteria, with TLR2, TLR4, TLR9 and NLRP3 being common to the fungi (Aspergillus, Candida and Cryptococcus species) most often associated with COVID-19, ALI/ARDS and sepsis." (PMID 33672738, 2021). "To determine whether the HMGB1/TLR2/MyD88 signaling pathway is involved in the therapeutic effect of Ts-AES on sepsis-induced ALI, we evaluated protein and mRNA expression levels of HMGB1, TLR2 and MyD88 in lung tissue 12 h after CLP surgery." (PMID 33842398, 2021). "Also, platelet production of this DAMP encourages monocyte accumulation at the site of vascular thrombosis via both RAGE and TLR2 and can promote neutrophil-mediated host defense mechanisms during sepsis." (PMID 32858930, 2020). "Extracellular HMGB1 and its receptors, RAGE, TLR2, and TLR4, have been implicated in mechanisms of many inflammatory diseases, including sepsis, atherosclerosis, and rheumatoid arthritis by induction of senescence-associated secretory phenotype via NF-kB activation." (PMID 33384655, 2020). "TLR2 Arg753Gln: AG genotypes and A allele; TLR4 Asp299Gly: CT genotype and C allele; TLR4 Thr399Ile AG genotype and A allele showed significant higher risk to sepsis as compared to other genotypes and alleles." (PMID 33247673, 2020). "ORM2 interacts with TLR2 signaling involved in the pathobiology of sepsis." (PMID 32174955, 2020). "TLR4 and TLR2 are involved in the control of splenic DC apoptosis during polymicrobial sepsis, suggesting that modulation of DC-specific TLR4/TLR2 signaling may be a new therapeutic strategy for the treatment of sepsis." (PMID 32197507, 2020). "Recently, we demonstrated that chronic L. sigmodontis infection protected mice against Escherichia coli-induced sepsis via TLR2-dependent macrophage modulation, resulting in a milder E. coli-induced hypothermia, reduced inflammation, improved bacterial clearance and sepsis survival." (PMID 31815088, 2019). "Thereby, TLR4 and TLR2 mRNAs are highly expressed in patients with sepsis." (PMID 31671729, 2019). "Among the TLRs, the most intensively expressed was TLR2, which was possibly a consequence of bacterial infection; this is not surprising considering that sepsis is a common cause of death among SS patients." (PMID 29190907, 2017).
Sepsis (continued). "Soluble TLR2 levels are elevated in infective and inflammatory conditions, but its diagnostic value with sepsis-induced multi-organ failure has not been evaluated." (PMID 28092080, 2017). "Notably, the course of sepsis caused by PSM-deficient S. aureus is similar in wild-type and TLR2-deficient mice, but TLR2 is required for protection of mice against PSM-producing S. aureus." (PMID 27470911, 2016). "Alternatively, the observed reduction in the different sepsis parameters could be mediated by distinctive L. sigmodontis-derived components of which at least the bacterial load was dependent on TLR2 signaling." (PMID 25611587, 2015). "Consistent with the results on hypothermia, bacterial clearance and macrophage responses, L. sigmodontis infection did not improve sepsis survival in the TLR2-deficient group." (PMID 25611587, 2015). "In the present study, we have investigated the effects of preventive and therapeutic administration of anti-TLR2 and anti-TLR4 mAbs, either alone or in combination, and in conjunction with antibiotic treatment in a model of polymicrobial sepsis caused by cecal ligation and puncture (CLP)." (PMID 26147469, 2015). "TLR4 and TLR2 signaling is the key pathway in sepsis pathophysiology." (PMID 26599367, 2015). "Finally, transfer experiments using in vitro modulated macrophages from wild type and TLR2-deficient mice demonstrated that exposure of macrophages to Wolbachia or LsAg improved E. coli-induced sepsis in a TLR2-dependent manner." (PMID 25611587, 2015). "In association, L.s. infection neither improved bacterial clearance in TLR2-deficient animals nor ameliorated E. coli-induced hypothermia and sepsis survival." (PMID 25611587, 2015). "Mechanistically, in severe sepsis, components of bacteria (such as TLR2 and TLR4 ligands) or mediators of inflammation may reach the circulation and activate circulating neutrophils leading to loss of CXCR2 from the surface of neutrophils." (PMID 26147469, 2015). "MFHAS1 may represent one of the factors that changes in the different stages of sepsis through TLR2, although the time span of the inhibitory effect of MFHAS1 is short." (PMID 26599367, 2015). "The findings of the current study reinforce the role of TLRs in the pathogenesis of sepsis and suggest that blockade of TLR2 or TLR4 may be a useful therapeutic approach to control systemic inflammation, organ injury and lethality in polymicrobial sepsis." (PMID 26147469, 2015). "However, the L. sigmodontis-mediated protective effect against an E. coli-induced sepsis was lost in infected TLR2-/- mice." (PMID 25611587, 2015). "Therefore, our preclinical experiments strongly suggest that there exists a therapeutic window in which to use anti-TLR2 or anti-TLR4 mAbs with antibiotics in patients with ongoing sepsis." (PMID 26147469, 2015). "However, the uncontrolled response after LPS recognition by TLRs results in sepsis and thus inhibiting TLR4 and TLR2 mediated signaling is an effective therapy for sepsis." (PMID 26198237, 2015). "The authors concluded that the allelic variants PLA2G2A, TLR2, TLR5 and IL-10 could influence the risk of sepsis among preterm infants." (PMID 24310803, 2013). "However, work by Zou and colleagues suggest protective effects of TLR2 knockdown during polymicrobial sepsis." (PMID 22970242, 2012). "Work with murine models of staphylococcal skin infections, arthritis and septicemia has led to the suggestion that IL-1R, that also signals through MyD88, is more important than TLR2 for neutrophil recruitment and bacterial clearance [, reviewed in Sethi and Chakraborty (2011)]." (PMID 23316483, 2012). "To date, TLR2 and TLR4 expression has been mainly studied in monocytes, and most studies show enhanced surface expression of TLR2 in sepsis, while the data concerning TLR2 surface expression in trauma and SIRS patients or TLR4 expression are more controversial." (PMID 23098236, 2012).